INS (insulin)
Diseases named in the same sentence as INS in open-access papers (continued):
Sharing a sentence is not in itself a finding about the gene and the disease.
diabetes (continued). "Induction of ICER by hyperglucagonemia may represent an additional mechanism contributing to deregulated insulin gene expression and β-cells failure in diabetes." (PMID 24672804, 2014). "Insulin, which is usually used in patients with T2DM, might provide certain role in the increased risk of CRC; concurrently diabetes situation might be associated with the contribution of insulin on the increasing risk of CRC." (PMID 24885616, 2014). "In general, the fasting insulin levels were higher in diabetes group." (PMID 25309595, 2014). "Long-term protection against diabetes led to preserved islet architecture and insulin expression." (PMID 24983882, 2014). "Alternatively, if insulin reverses the chronic immunosuppressive effects of diabetes and restores the balance in inflammatory response, then insulin may be potentially beneficial." (PMID 24587357, 2014). "Both estriol and progesterone might be involved in the prevention of type 1 diabetes mellitus through the hepatic insulin synthesis even when the pancreatic insulin synthesis was impaired." (PMID 24711743, 2014). "Thus, insulin should be measured in clinical situations to allow the earlier detection of diabetes mellitus." (PMID 24949486, 2014). "Recent knockout studies, suggested that inhibition of TXNIP/TBP-2, up regulates both insulin sensitivity and glucose-stimulated insulin secretion in diabetes, and might present a novel therapeutic approach for T2DM." (PMID 24624334, 2014). "Diabetes of the patient described in our report was originally clinically classified as LADA; however, ketoacidotic manifestation of the disease and requirement of urgent insulin treatment suggest acute manifested insulin-dependent diabetes mellitus corresponding with ketosis-prone diabetes (KPD)." (PMID 24711951, 2014). "It is well known that high-dose STZ severely impairs insulin secretion, mimicking type 1 diabetes mellitus, and low-dose STZ after high-fat diet feeding induces a mild damage to beta cells on the background of insulin resistance, which is similar to the features of T2DM pathogenesis." (PMID 25177707, 2014). "Perturbations in insulin secretion are a common feature of several genetic forms of diabetes." (PMID 25144761, 2014). "We herein present novel evidence that decreased baseline serum vaspin is an independent risk factor for subsequent occurrence of diabetes in non-diabetic subjects and higher percentage of insulin treatment in diabetic patients." (PMID 24732788, 2014). "T2D medication to control diabetes (hypoglycemic drugs and/or insulin)." (PMID 24485048, 2014). "With a steady increase in the number of patients with diabetes, a longer life expectancy of diabetic patients, and the clinical benefits of intensive glycemic control, oral hypoglycemic agents or insulin are consequently expected to be used more often in combination with metformin." (PMID 25299054, 2014). "Insulin is positively associated with the growth of both normal and cancerous prostate cells, and, therefore, decreased insulin production, as observed in people with diabetes, may inhibit cell growth." (PMID 23668396, 2014). "Participants were asked to self-report whether they had been told by a doctor that they had diabetes mellitus or high blood sugar, whether they use pills or other medicines because of diabetes or high blood sugar, and whether they used insulin injections." (PMID 24884735, 2014). "A significant relationship has been demonstrated between insulin concentration and the risk of cardiovascular death, independent of other established risk factors, in people without diabetes." (PMID 25024747, 2014). "Chronic hyperglucagonemia usually parallels defective insulin secretion in diabetes." (PMID 24672804, 2014). "So, the increasing of hepatic insulin sensitivity will not be effective in reducing these cardiovascular risk factors in women with parental diabetes in prevention strategies proposed in these women after GDM." (PMID 25097861, 2014).
diabetes (continued). "Interestingly, glycemic control by insulin administration prevented the diabetes-induced increase in the serum and urine ACE2 activity in the Diabetic mice." (PMID 24400109, 2014). "Insulin treatment significantly reversed diabetes-induced cerebral peroxynitrite production." (PMID 25223305, 2014). "Metformin is an effective insulin sensitizer treating type 2 diabetes mellitus." (PMID 24963493, 2014). "On these bases, the aim of our study was to investigate whether GA levels are elevated in subjects with long duration of diabetes in close connection with their insulin secretory capacity." (PMID 25265016, 2014). "However, bias from undiagnosed diabetes (or insulin use) would be expected to decrease the effect sizes found." (PMID 24919660, 2014). "Hence, this study aimed to characterize endothelial biomarkers in relation to impaired insulin sensitivity and progression to overt diabetes early after index pregnancy." (PMID 25281032, 2014). "Seven patients had diabetes mellitus requiring insulin therapy." (PMID 24475137, 2014). "Disturbance of zinc homeostasis has been accepted as one of the most crucial signs of diabetes because diabetic patients experience an increased urinary excretion of zinc and zinc is involved in the synthesis, secretion as well as function of insulin." (PMID 24587273, 2014). "Diabetes mellitus (DM), which affects manyorgans in the body, is one of the most prevalentmetabolic disorders in all parts of the world.Insulin and oral natural or synthetic hypoglycemicagents are used to treat DM but these drugstreat rather than cure the disease and have noticeableside effects." (PMID 24567945, 2014). "Based on an initiative of the German Mukoviszidosis-Foundation, the present study tries to answer the question, whether oral therapy with repaglinide is as effective as insulin therapy in cystic fibrosis patients with early diagnosed diabetes mellitus." (PMID 24620855, 2014). "Insulin is widely used in patients with type 2 diabetes mellitus (T2DM)." (PMID 24885616, 2014). "Notably, decreased phagocytosis, killing of bacteria, and production of reactive oxygen species have long been observed in PMN from diabetic patients or in animal models of diabetes, which can be reversed by insulin treatment to restore glucose balance." (PMID 24595889, 2014). "Fourteen candidate predictors (age, sex, BMI, smoking status, systolic blood pressure, macrovascular complications, insulin dependency, duration of diabetes, retinopathy, treatment modality, Karnofsky scale, hemoglobin level, serum phosphate and serum albumin) were included in this analysis." (PMID 24594735, 2014). "Interestingly, we have observed significant reduction in S1P content in case of streptozotocin-induced diabetes, which is even more interesting given the fact that S1P stimulates pancreatic β-cells growth and promotes insulin secretion." (PMID 24701589, 2014). "“Negative feelings about living conditions with diabetes” was significantly associated with interdependence, perceived emotional support, HbA1c and insulin." (PMID 25333692, 2014). "A higher incidence of peripheral neuropathy among insulin-treated people could be attributed to the longer duration of diabetes, delay in insulin treatment and possible insulin neuritis at the time of neurological examination." (PMID 24593991, 2014). "These active constituent have antioxidants properties which may be very important in mitigating impaired insulin secretion and action in insulin resistance and prevent diabetes complications." (PMID 25114929, 2014). "Further support of an association between early life BMI and diabetes risk is evident from our life course approach; for serum insulin none simpler model (sensitive period, mobility or accumulation models) fitted the data as well as the saturated model." (PMID 25474626, 2014).
diabetes (continued). "Types 1 and 2 diabetes were successfully induced and rabbits could be differentiated based on their fasting insulin, glutamic acid decarboxylase autoantibody, and insulin autoantibody levels." (PMID 25182068, 2014). "Based on an initiative of the German CF-Foundation (Mukoviszidose e.V.), the present study tries to answer the question, whether oral therapy with repaglinide is as effective as insulin therapy in CF patients with early diagnosed diabetes mellitus." (PMID 24620855, 2014). "While insulin resistance is a cardinal pathogenic feature of T2DM, affecting 90–95% of patients, diabetes does not occur until the pancreatic islet β‐cell no longer produces insulin in a rate sufficient to fully compensate for the impaired insulin sensitivity." (PMID 24872354, 2014). "Among a variety of metabolic and cytoprotective activities reported so far, CT-1 has been shown to play an important protective role in beta-cell viability and to improve glucose-stimulated insulin secretion, and moreover, to prevent streptozotocin-induced diabetes in mice." (PMID 25025664, 2014). "T1D indicates the process of β-cell destruction that may ultimately lead to diabetes mellitus in which “insulin is required for survival” to prevent the development of ketoacidosis, coma, and death." (PMID 25162051, 2014). "In the non-obese diabetic (NOD) mouse model of T1D, insulin is an essential autoantigen and mice with certain mutations in the insulin gene do not develop diabetes." (PMID 25393309, 2014). "Due to a research of Spiegelman as he mentioned, the pancreas activation of SIRT1 can increase the pancreas insulin secretion, resulting in gluconeogenesis in the liver, which may treat diabetes adversely." (PMID 25386563, 2014). "However, as diabetes duration increased, the level of ΔC-peptide, an insulin secretory index of β-cells, was statistically decreased, indicating the gradual deterioration of reserve β-cell function over time." (PMID 25265016, 2014). "Clinical studies have shown normal insulin sensitivity, but reduced glucose-stimulated insulin secretion in subjects with pre-diabetes with HNF-4A MODY, suggesting that pancreatic β-cell dysfunction rather than insulin resistance is the primary defect in this disorder." (PMID 24299156, 2014). "Type 1 diabetes mellitus, which is characterized by a lack of insulin production, is associated with decreased skeletal mass." (PMID 24348809, 2014). "Expression of these over-active KATP channels render β-cells functionally inexcitable, causing an absence of insulin release, marked hyperglycemia and diabetes." (PMID 25188228, 2014). "The long diabetes duration and insulin treatment may affect the vaspin levels and thus induce the decrease of vaspin in our T2DM group than in non-diabetic group." (PMID 24732788, 2014). "Furthermore, the reason for the recovery of liver function is related to presenting normal levels of blood glucose and insulin levels in the blood after treatment of diabetes." (PMID 23579248, 2014). "Notably, most of the downregulated genes have been implicated in diabetes pathogenesis; SLC2A2 (Glut2) is involved in β-cell function and insulin secretion." (PMID 25379510, 2014). "Patients' records were reviewed to obtain data pertaining to age, sex, marital status, Body Mass Index (BMI), level of education, smoking status, duration of diabetes mellitus, glycemic control using HbA1C test, use of insulin, and presence of additional illnesses." (PMID 24524353, 2014). "Multiple diabetes medication reductions occurred for five participants, whilst four participants ceased all diabetes medication during the study, including one participant who was taking insulin at baseline." (PMID 24886191, 2014). "For example, MET reduced the development of T2DM by 31% in the US Diabetes Prevention Program study, presumably through its indirect effects to reduce β-cell workload (inhibition of hepatic glucose production and improved hepatic insulin sensitivity)." (PMID 24524730, 2014).
diabetes (continued). "Insulin and glucose levels of blood plasma are the primary markers of diabetes." (PMID 25114914, 2014). "Diabetes is defined by a person's inability to maintain proper blood insulin levels." (PMID 25120571, 2014). "An oral glucose tolerance test demonstrated impaired glucose tolerance and diabetes mellitus with marked insulin resistance (the peak insulin level for each patient was 197 and 279 μU/mL, respectively, while the 120’ insulin level of each patient was 167 and 234 μU/mL, respectively)." (PMID 24479866, 2014). "Of 3,870 participants between ages 12 and <80 having data on urinary phthalate metabolites, fasting glucose and insulin levels, we excluded n = 322 people who self-reported ‘yes’ or ‘borderline’ for diabetes diagnosis status, refused, or had missing information." (PMID 24499162, 2014). "The presence of known insulin sensitizers and AG inhibitors like phloretin-2 glucoside, oleanolic acid and beta-sitosterol in SC play an important role in these multifaceted activities of SC with respect to diabetes." (PMID 25184241, 2014). "Additionally, studies in Sweden and those conducted in Pima Native Americans have shown that the acute insulin secretory response to intravenous glucose is an independent predictor of the development of diabetes." (PMID 25166121, 2014). "Indeed, the actual duration of exposure to elevated insulin levels cannot be reliably assessed even when precise date of diagnosis was known, as insulin resistance can predate the diagnosis of diabetes by up to 10 years." (PMID 25419576, 2014). "Therefore, in the present study, the clinical profiles of Japanese type 2 DM patients who were switched from insulin to lira by a diabetes specialist as part of routine outpatient care were retrospectively collected and analyzed." (PMID 24578756, 2014). "For patients with both HCC and diabetes mellitus, metformin and thiazolidinediones may be better choices than insulin use." (PMID 24830459, 2014). "In addition, recent experiments have shown that mucosal administration of insulin or gene disruption of insulin prevent the onset of diabetes in the NOD model of diabetes." (PMID 24629100, 2014). "Patients with diabetes prescribed insulin had increased mortality (hazard ratio 1.97)." (PMID 25361884, 2014). "Insulin administration is only performed for pregnant women who fail to maintain glycemic goals as well as to the ones who show signs of excessive fetal growth or overt diabetes." (PMID 25197655, 2014). "Together, these data demonstrate a critical new role for SOX17 in regulating insulin trafficking and secretion and that modulation of Sox17-regulated pathways might be used therapeutically to improve cell function in the context of diabetes." (PMID 25144761, 2014). "Finally, the major anxious depression class showed a significantly younger age at onset of diabetes, higher HbA1c levels, higher serum triglycerides levels and a higher frequency of insulin use than the other three classes." (PMID 25390370, 2014). "Our results also show adiponectin to be associated with metabolic syndrome and diabetes-related qualitative traits, whereby adiponectin was associated with increased HDL-c and IS; and decreased BMI, waist circumference, insulin, HOMA-IR and HOMA-β; which is in line with previous studies." (PMID 25276234, 2014). "Similarly, daily olive leaf extract supplementation (500 mg/day for 14 weeks) lowered HbA1C and fasting plasma insulin levels in adults with type 2 diabetes mellitus." (PMID 25379688, 2014). "The pro-insulin factor, IGF-1 is known to confer insulin-like action to stimulate glucose uptake and its mal-regulation is recognized to associate with insulin resistance and diabetes." (PMID 24498028, 2014). "Insulin detemir is preferred over insulin glargine for diabetes treatment during pregnancy." (PMID 25197671, 2014).
diabetes (continued). "Indeed, there are mixed findings with regards to changes in quality of life in persons with diabetes treated with the insulin pump compared with multiple daily injections system." (PMID 25303963, 2014). "The variables that were significantly different between the 1st quartile and 4th quartile of the eGDR formula data comprise age, duration of diabetes, BMI, thoracic-abdominal fat (absolute and percentage), total dose insulin IU/lean mass (kg), arm fat, waist/height ratio and scapular skinfold." (PMID 25937839, 2014). "Control of diabetes (HbA1c) was directly correlated with type of anti-diabetic medication (oral anti-diabetic drugs or insulin included medication), and the same indices (including PLI, CAL) and xerostomia, which increased in poor control of diabetes, increased in insulin-dependent patients." (PMID 24495383, 2014). "In this study, diabetic men receiving insulin treatment had nearly double the risk of fractures compared with those without diabetes after adjustment for multiple covariates." (PMID 25140176, 2014). "A better understanding of how iron and insulin signaling are coordinated in C. elegans could provide new knowledge about the role of iron in glucose metabolism and in the pathogenesis of diabetes in humans." (PMID 24904417, 2014). "Application of glibenclamide (1–10 μM), a well-known diabetes drug that promotes insulin secretion by inhibiting KATP22, to RINm5F cells depolarized the membrane as expected; however, in the presence of glyH-101 (10 μM), the glibenclamide-induced membrane depolarization was significantly reduced." (PMID 25025956, 2014). "Despite diabetes was found to be a risk factor for cancer related mortality in GC, insulin use did not affect the outcomes." (PMID 24599168, 2014). "The concentration of insulin is much lower in patients with type 1 diabetes mellitus than in healthy individuals, which may impact the skeletal response to mechanical loading in these patients." (PMID 24348809, 2014). "Vanadium compounds, in particular organic derivatives, are effective oral insulinomimetics, which inhibit lipolysis, decrease blood glucose levels (BGL) in animals and in clinical trials, and stimulate insulin secretion in experimental models of Diabetes Mellitus (DM)." (PMID 25057899, 2014). "Therefore, it is a potential insulin-sensitizing agent in type 2 diabetes mellitus with insulin resistance." (PMID 24438349, 2014). "...In August, I started with insulin and every 2 weeks I called my diabetes nurse." (PMID 25340869, 2014). "Considering the pandemic incidence of diabetes and comorbid sleep disordered breathing (SDB) particularly during pregnancy, a report showing a cause-effect relationship between IH challenge and insulin deregulation via a disturbed zinc homeostasis is crucial." (PMID 24587273, 2014). "The multiplicity of the bacteria was less profound in the colon, which might explain why the diabetes-related structural alterations in the mesenteric capillaries here were only partially restored in the insulin-treated diabetic rats." (PMID 25469509, 2014). "Insulin dysfunction, manifested by diabetes mellitus (DM) might be such factor, as there is extensive data from epidemiological studies suggesting that DM is associated with an increased relative risk for AD." (PMID 24574966, 2014). "This suggests that pre-existing thyroid disease may dysregulate metabolic control in newly diagnosed diabetes necessitating earlier insulin therapy." (PMID 24580798, 2014). "Participants in our study had type 2 diabetes mellitus for mean 12.0 years and in the practical points, more patients reached an HbA1c level of 7.5% or less with insulin glargine plus glimepirde plus metformin than with insulin glargine plus metformin." (PMID 24614911, 2014).